MMP2 (matrix metallopeptidase 2)
Diseases named in the same sentence as MMP2 in open-access papers (continued):
Sharing a sentence is not in itself a finding about the gene and the disease.
cancer (continued). "In particular, γ-IR-treated cancer cells or mouse xenografts and metastatic lesions in mice bearing γ-IR-treated xenografts also display typical EMT marker expression patterns, such as increased vimentin or MMP-2 expression, decreased E-cadherin, and enhanced activity of MMP-2." (PMID 22963683, 2012). "Therefore, the inhibition of migration or invasion mediated by MMP-2, MMP-9 or u-PA could be a way to prevent or inhibit cancer metastasis." (PMID 19789215, 2011). "We thus tested whether THL could inhibit the secretion of MMP-2, MMP-9, and uPA in cancer cells." (PMID 20429953, 2010). "The induction of the expression of MMPs, including MMP-2 and MMP-9 is well demonstrated in the context of cancer metastasis and is purported to play a role in both angiogenesis and cellular invasiveness by contributing to the enhanced migratory phenotype of the cancer cell." (PMID 20051102, 2010). "If such a hypothesis is true, it might be expected that infiltrative cancers would express higher levels of hypoxia inducible factor (HIF-1α), which in turn would upregulate a number of downstream mediators including various proteases, such as MMP2." (PMID 17353920, 2007). "In contrast, there was significantly decreased expression of MMP2 and MMP23, maspin, and the protease inhibitors tissue inhibitor of metalloproteinase 3 (TIMP3), TIMP4 and RECK (reversion-inducing cysteine-rich protein with Kazal motifs) in the cancer specimens." (PMID 15928670, 2005). "Genes upregulated by >1.5‐fold in cancer tissues rather than in normal intestinal mucosae include Wnt signaling‐related genes such as Fzd1 (fold change [FC], 5.6), Myc (FC, 2.6), Ccnd1 (FC, 1.6), Mmp2 (FC, 10.4), Mmp7 (FC, 16.0), Mmp8 (FC, 12.9), Mmp12 (FC, 52.2), and Spp1 (FC, 149.3)." (PMID 35274815, 2022). "However, upregulated expressions of MMP-2 and MMP-9, accompanied by downregulated TIMPs, were found in high-grade tumors, suggesting that interrupting the delicate balance between MMPs and TIMPs could affect tumor cell migration and cancer metastasis." (PMID 33535458, 2021). "In addition, AKR1B10 promotes cancer metastasis through activation of the ERK signaling pathway, which stimulates the downstream integrin α5/δ-catenin mediated FAK/Src/Rac1 signaling pathway and increases the expressions of matrix metalloproteinase-2 (MMP2) and vimentin." (PMID 34063865, 2021). "MMPs (MMP2 and MMP9) were also highly expressed in the PCa samples examined in this study, suggesting that expression of MMPs is activated in PCa and may enhance cancer invasion and metastasis, providing further evidence that ANT2 plays an important role in development of PCa." (PMID 34539732, 2021). "Furthermore, the downregulation of the intrinsically higher levels of MMP2 and MMP9 by COL1 in resistant W1CR cells confirm the discrete regulation of both resistance pathways and offer interesting new targets for clinical sensitization strategies in the treatment of cancer patients." (PMID 33287446, 2020). "Besides, qRT‐PCR and immunohistochemistry assays were performed to evaluate the expression of VEGF, MMP‐2, and MMP‐9 related to the invasion and metastasis of cancer, and the results showed that Sanhuang decoction could significantly inhibited the expression of VEGF, MMP‐2, and MMP‐9." (PMID 31762993, 2019). "Interleukin (IL)-6 drives many of the cancer ‘hallmarks’ through downstream activation of the Janus kinase/signal transducer and activator of transcription 3 (JAK/STAT3) signaling pathway, we wanted to find whether STAT3 plays a role in IL-6-induced MMP2 and MMP9 expression." (PMID 31409371, 2019). "The canonical proteolytic cascade that leads to enhanced cancer cell invasion is considered to be initiated by (pro)cathepsin B, which translocates from lysosomes to plasma membranes, where it may activate uPA, which in turn activates MMP-14, followed by activation of gelatinases MMP-2 and MMP-9." (PMID 28424417, 2017).
cancer (continued). "Invitro studies using HA22T cancer cell line, treatment of Zanthoxylum avicennae extract not only suppressed cell proliferation through induction of G2/M cell cycle arrest and apoptosis, but also inhibited cell metastasis, invasion via downregulating MMP-2/-9 and upregulating TIMP-1/-2." (PMID 26978396, 2016). "MT1-MMP localizes to the plasma membrane to induce MMP-2 activation, and that intracellular trafficking of subcellular organelles may be regulated by mDia1; therefore, we hypothesized that mDia1 could be involved in the localization of MT1-MMP to the plasma membrane to induce cancer cell invasion." (PMID 26893363, 2016). "MP1 was modified by addition of sequences allowing binding to the cancer biomarker EGFR, with or without sequences directing cleavage by the cancer biomarker MMP-2." (PMID 41920242, 2026). "Results of this analysis showed a significant increase in MMP2, MMP9, MMP12, and MMP16 levels in KIRC patients across different cancer stages, races, genders, and age groups when compared to normal controls." (PMID 38560573, 2024). "In conclusion, not all leaf extracts can decrease the activity of both MMP-2 and MMP-9 in cancer, which emphasizes the value of the tested chokeberry leaf extracts." (PMID 39683504, 2024). "Compared with placebo control, bosentan treatment did not significantly change the mRNA levels of Cyclin D1, MMP2, Vimentin and ETB under conditions of fibrocyte depletion, except leading to a slight downregulation of mRNA expression of ETA in cancer cells." (PMID 36241617, 2022). "Moreover, many studies revealed a correlation between increased MMP-2/9 expression and worst outcome of CRC suggesting that the control of the expression and/or the activity of these proteolytic enzymes may offer a new therapeutic opportunity for treating this highly invasive cancer." (PMID 35887021, 2022). "Although MMP-2 and MMP-9 (gelatinase B) are factors studied in inflammation and cancer, they are not vastly important in skin aging reactions." (PMID 34122721, 2021). "For the six remaining NETs-related lncRNAs (AC020765.2, SCAMP1.AS1, AL035587.1, AP000695.2, AP004608.1, and MMP2.AS1), there have been no studies exploring their potential roles in the development of cancer at present." (PMID 34257164, 2021). "The inhibitory effect of TIMP-2-specific inhibition on MMP-2 (previous findings show a strong balance between MMP-2 and TIMP-2 in the case of cancer cells) can explain the observed lack of TIMP-2 overexpression in PsA patient plasma." (PMID 34691360, 2021). "In the present study, changes in the expression of MMP2, MMP9, and MMP16 genes between patients with AML and people without cancer were examined." (PMID 34035811, 2021). "Compared to the expression levels of MMP-2 in each cancer cell line that was not treated by either TAO or VEGF, TAO reduced MMP-2 by about 40% in HeLa and 60% in CaSki cell lines." (PMID 33086573, 2020). "Although the inhibition of the T-box transcription factor Brachyury is shown to downregulate MMP2 and MMP24 in cancer, to date, there are no reports on the direct participation of TBX4 in MMP gene expression." (PMID 31311130, 2019). "Likewise, establishing how CP1/CTSL facilitates ASP invasion, characterizing the signal released by MMP2 to laterally inhibit tip cell fate, and determining how proteolytic enzymes cooperate during ASP development might provide new insights regarding ECM remodeling in human cancer progression." (PMID 30018198, 2018). "In our study, MMP2 (and MMP9 for LNCaP) were produced by cell tumors in inactive forms and Apixaban did not activate the MMPs produced by cancer cells." (PMID 29023465, 2017).
cancer (continued). "Although MMP2 and MMP9 have been shown to be upregulated in many cancers and enriched at the invadopodia, there are no defined pathways that describe how these enzymes are transported to specific ECM degradation sites that facilitate metastasis." (PMID 27789576, 2016). "The levels of MMP-2 and MMP-9 were significantly higher in carcinomas than in peritumoral tissue, irrespective of MMP type or activity state." (PMID 24778099, 2014). "No prior study has shown an effect of HMGB1 on MMP-2 and TIMP-3 whereas it has been recently reported that HMGB1 enhances MMP-9 expression in neurons, via Toll-Like Receptor 4 signaling, and in cancer cells via NF-κB signalling." (PMID 21731608, 2011). "Cancer cell spheroids disaggregated on extracellular matrices (ECM) and demonstrated enhanced expression of secreted pro-MMP2 as well as activated MMP2/MMP9 with no such activation of MMP's observed in monolayer cells." (PMID 17567918, 2007). "MMP-2 and MMP-14 expression by cancer cells was not evaluated because too few cases expressed those markers." (PMID 16776850, 2006). "We also observed the same trend for the mRNA of the mesenchymal marker hFN1, suggesting an increased aggressiveness of cells accompanied by an increase in MMP2 but not MMP9 mRNAs and of the CDH5 gene, fundamental to sustain cancer cell proliferation through vasculogenic mimicry." (PMID 40332096, 2025). "Cryptolepine had no obvious effects on MMP2 and MMP9 expression in unstimulated cells but significantly reduced WNT3a-induced expression of these genes, confirming the selectivity of cryptolepine for cancer cells with hyperactive WNT signaling." (PMID 37513937, 2023). "The change in the expression of MMP2 and MMP9 concerned only cancer cells and no other cells." (PMID 37509417, 2023). "MMP-2 and Fibronectin were categorized as type I (developmental), and type II (fibrosis and wound healing) specific EMT markers, but not the type III EMT marker (cancer), indicating that arsenic activates the fibrogenic-type EMT." (PMID 37675120, 2023). "Although Raf/MEK/ERK-mediated regulation of transcription factors is involved in the regulation of MMP13 by RKIP, it has been determined that this pathway is not required for the observed invasive nature of cancer cells with regards to RKIP and MMP1 and MMP2 in vitro." (PMID 36765912, 2023). "A study on MMP-2/9 expression and drug resistance conducted with epirubicin revealed that the expression of MMP-2/9 has been significantly higher in epirubicin-resistant cancer cells than non-resistant cancer cells." (PMID 33768509, 2021). "They found that EEOS inhibited cancer invasion and MMP-9 activity, but not that of MMP-2." (PMID 32102512, 2020). "Although this ligand may be useful for imaging MMP9 expressing cancers, the lack of MMP9 specificity of the ligand could result in low signal-to-noise ratio, as MMP2 presence in normal tissues is more widespread compared to MMP9." (PMID 33007872, 2020). "Therefore, although MMP-2 and -9 participate in the signaling pathway related to cell migration and invasion induced by XCL1 in various cancer cell types, these MMPs do not appear to contribute to the XCL1-induced promotion of MDA-MB-231 cell migration." (PMID 33374849, 2020). "However, longer incubation of WHCO1 and MDA MB 231 cells with WJ-MSCs did not result in sustained downregulation of PCNA, BCL-2, MMP-2, and c-MYC gene expression in the cancer cells indicating that the effect of coculture is transient." (PMID 26880967, 2016). "The mechanisms mediating S100A8 and S100A9 regulation of MMP2 and MMP9 expression in cancer cells are not yet known but may involve their calcium-binding activity." (PMID 27086923, 2016). "Our results show that PMS can inhibit the growth of cancer cells without side effect on normal cells, as well as their ability of invasion and metastasis, while reducing the MMP9 and MMP2 activity." (PMID 26674531, 2015).
cancer (continued). "VEGF, TRAILR2, MMP2 and MMP11 were not regulated by the cancer cell conditioned medium." (PMID 26362269, 2015). "We found that rapamycin significantly inhibited MMP-2, but not MMP-9, compared with the control, suggesting that mTOR signaling plays significant roles both in maintaining NPC CSCs and in cancer progression." (PMID 26202311, 2015). "Furthermore, high TIMP-2 expression by cancer cells was present in 225 (41.7%) cases while cancer cells expressed MMP-14 in 4 (0.7%) cases and none expressed MMP-2." (PMID 16776850, 2006). "As the FGF2 rs1048201, PDGFRB rs246395, PDGFRA rs2228230, MMP2 rs243865, rs7201, and TIMP2 rs7501477 have not been previously examined in HNSCC in terms of survival and treatment outcome, this is most likely the first report describing their prognostic and predictive value in this type of cancer." (PMID 35406617, 2022).
infection (93 papers, 2007 to 2025). The state of being infected such as from the introduction of a foreign agent such as serum, vaccine, antigenic substance or organism. "Environmental triggers, such as hypoxia, hemorrhage, and infection, act synergistically with MMP2 promoter variants to enhance matrix degradation and vascular permeability." (PMID 41464177, 2025). "Immunohistochemical staining results showed that a longer infection time was associated with an increased number of cells staining positive for MMP-2, FAK and p-FAK." (PMID 24348806, 2014). "Epithelial derived MMP-2 protects the epithelial barrier integrity and promotes healing, which is compromised in MMP-2 deficient mice and may lead to their increased susceptibility to STm infection." (PMID 35733975, 2022). "In case of MMP2 rs243866 and rs17859821 positions, one or both copies of the mutant allele (Adenine) increased the likelihood of congenital infection, whereas, for rs2285053, both T alleles are needed for susceptibility to infection." (PMID 31474955, 2019). "After infection, Mfsd2a, MMP2 and MMP9 showed significantly up-regulation (P<0.05), while CAV-1 expression was significantly down-regulated (P<0.05), indicating that vesicle transport efficiency or barrier permeability was affected." (PMID 40642060, 2025). "At 4 h post-infection, the rNRP2-infected group exhibited a sevenfold increase in MMP-2 expression compared to control cultures, the highest observed level." (PMID 41450943, 2025). "By 24 h post-infection, MMP-2 secretion reached similarly high levels across all infected tissues, regardless of the Mtb phase." (PMID 41450943, 2025). "In our ex vivo model, MMP-2 showed a marked increase as early as 4 h post-infection, particularly in explants exposed to late reactivation-phase bacilli (rNRP2), reaching up to sevenfold higher levels than control." (PMID 41450943, 2025). "Infection with Brucella induces high expression of MMP-2 and pro-inflammatory mediators, including IL-6, IL-8, MCP-1, and granulocyte-macrophage colony-stimulating factor (GM-CSF) in synovial cells." (PMID 39967734, 2025). "The expression of MMP-2 in corneal epithelial cells increased approximately 5-fold after their infection with CEES." (PMID 39359528, 2024). "In an in vitro model of infection using human fallopian tube explants, C. trachomatis infection induced production of MMP2 and MMP9 by infected epithelial and stromal cell populations, respectively." (PMID 37265500, 2023). "Here our results showed that the immune response to a mild infection simulated by low-dose LPS induced inflammatory factor IL-1b expression and decreased MMP2 expression involved in embryo implantation." (PMID 36910123, 2022). "Our results indicated potential immunosuppressive mechanisms during the infection of MP and the decrease of sIL-6Rβ and MMP-2." (PMID 36618370, 2022). "Elastase A, elastase B, proteinase IV and alkaline proteases activate host matrix metalloproteinases (MMPs) to establish infection by converting pre-MMP-2 to active MMP-2." (PMID 36313111, 2022). "In the kidneys of mice with decreased immune response, the MMP-2 activity increased with the duration of the infection." (PMID 34205319, 2021). "Then during the mice infection, a similar upregulation of MMP-2 fraction was observed by different methods of analysis." (PMID 33891967, 2021). "In NEC, elevated intestinal expression of ECM-associated proteins, especially MMP-2, −9 and TIMP-1,−2, facilitates the recruitment of immune cells to cross the endothelial and epithelial layers and reach the infection sites." (PMID 33133078, 2020). "The relative expression levels of MMP-2 mRNA at 0 d, 2 d, 7 d, 14 d, and 28 d after infection in HSK mouse model were 1.00±0.00, 1.59±0.04, 2.02±0.15, 2.70±0.26, and 1.99±1.86, respectively." (PMID 31061823, 2019).